NUDT9 (nudix hydrolase 9)
Description:
Hydrolyzes ADP-ribose (ADPR) to AMP and ribose 5'-phosphate. Has also a weak phosphohydrolase activity against NADH and FAD (in vitro).
Synonyms: MGC3037
Tractability: Small molecule: a structure with a bound ligand is known; it has a high-quality binding pocket. PROTAC: its protein half-life has been measured.
Target class: Enzyme; Hydrolase
Gene: Protein-coding gene on chromosome 4 (87,422,573 to 87,459,455, forward strand). Ensembl gene ENSG00000170502.
Subcellular location: Mitochondrion (Isoform 1); Mitochondrion; Cytoplasm
Subcellular location (Human Protein Atlas): Mitochondria; Nuclear bodies; Cell Junctions; Nuclear membrane
Pathways (Reactome):
Metabolism: Phosphate bond hydrolysis by NUDT proteins
Gene Ontology:
Molecular function: ADP-ribose diphosphatase activity; protein binding; ADP-sugar diphosphatase activity
Biological process: nucleobase-containing small molecule metabolic process
Cellular component: cytoplasm; cytosol; extracellular exosome; mitochondrion; mitochondrial matrix
Genetic constraint (gnomAD): Loss-of-function variants: 21 observed, 28.54 expected, observed/expected ratio (o/e) 0.74, 90% interval 0.52 to 1.06. The upper end of that interval is the gene's LOEUF score, 1.06, which puts it in group 4 of 6, group 1 being the genes least tolerant of losing a copy. Missense variants: 277 observed, 323.75 expected, observed/expected ratio (o/e) 0.86, 90% interval 0.77 to 0.94. Synonymous variants: 114 observed, 118.68 expected, observed/expected ratio (o/e) 0.96, 90% interval 0.82 to 1.12.
Homologues: Orthologues: chimpanzee NUDT9 (98% identical), macaque NUDT9 (95% identical), guinea pig NUDT9 (89% identical), mouse Nudt9 (89% identical), rat Nudt9 (89% identical), rabbit NUDT9 (87% identical), dog NUDT9 (87% identical), pig NUDT9 (81% identical), zebrafish nudt9 (51% identical), tropical clawed frog gdpd3 (51% identical), Drosophila melanogaster spd-2 (16% identical), Caenorhabditis elegans ndx-6 (6% identical).
Diseases named in the same sentence as NUDT9 in open-access papers:
NUDT9 is named in the same sentence as 7 diseases in open-access papers, as found by Europe PMC text mining. Sharing a sentence is not in itself a finding about the gene and the disease. The quoted sentences say what the papers report.
hepatocellular carcinoma (1 paper, 2021). A malignant tumor that arises from hepatocytes. "Upon initial exploration of the relationship between this gene and hepatocellular carcinoma cell (HCC), we observed that YAP, OGT, SLC5A3, and Nudt9 expression in HCC tissues was upregulated relative to that in normal liver tissues through The Cancer Gene Atlas (TCGA) online visualization website." (PMID 34588426, 2021).
liver cancer (1 paper, 2021). An epithelial or non-epithelial malignant neoplasm that arises from the liver. "We found that the expression of SLC5A3 and Nudt9 was positively associated with YAP and that their levels were elevated in liver cancer tissues." (PMID 34588426, 2021). "Activation of the HBP pathway is the foundation of enhancing the O-GlcNAcylation level in liver cancer cells, and Nudt9 and SLC5A3 are key genes of the HBP pathway." (PMID 34588426, 2021). "Also, we found higher levels of YAP OGT, SLC5A3, Nudt9, and O-GlcNAcylation in liver cancer tissues than in peritumoral tissues." (PMID 34588426, 2021). "Our previous research stated that, in an HG environment, after the level of YAP in liver cancer cells increased, global cellular O-GlcNAcylation could be upregulated through the regulation of Nudt9, SLC5A3, and OGT." (PMID 34588426, 2021). "However, CA reduced the expression of Nudt9, SLC5A3, OGT, YAP, and O-GlcNAcylation in liver cancer cells cultured in HG." (PMID 34588426, 2021).
cancer (4 papers, 2017 to 2024). A tumor composed of atypical neoplastic, often pleomorphic cells that invade other tissues. "RALGPS1, NUDT9, NUDT2, and PDE4A were less expressed in cancer cell lines; JUP, ADA, HPRT1, and IMPDH1 were highly expressed in cancer cell lines in CCLE." (PMID 34745385, 2021).
tumor (2 papers, 2015 to 2024). "Adenosine diphosphate ribose (ADPR) interacts with NUDT9 homology to activate transient receptor potential melastatin 2 (TRPM2) channel, while the decreased level of TRPM2 was considered to enhance tumor potential metastasis." (PMID 38596213, 2024).
NUDT9 also shares sentences with these, for which no sentence is quoted: breast carcinoma (4 papers); hypertrophic cardiomyopathy (1); ovarian carcinoma (1).